MIR8089 (microRNA 8089)
Synonyms: hsa-mir-8089
Gene: MicroRNA gene on chromosome 5 (181,043,403 to 181,043,484, reverse strand). Ensembl gene ENSG00000277912.
Homologues: Orthologues: chimpanzee MIR8089 (100% identical).